ABCF2 (ATP binding cassette subfamily F member 2)
Synonyms: HUSSY-18; EST133090; ABC28; M-ABC1; HUSSY18
Tractability: Antibody: its Gene Ontology location is reachable by antibodies, with high confidence. PROTAC: ubiquitination databases record sites on it; its protein half-life has been measured.
Gene: Protein-coding gene on chromosome 7 (151,211,484 to 151,227,241, reverse strand). Ensembl gene ENSG00000033050.
Subcellular location (Human Protein Atlas): Cytosol
Pathways (Reactome):
Cellular responses to stimuli: NFE2L2 regulating MDR associated enzymes
Gene Ontology:
Molecular function: ATP binding; ATP hydrolysis activity
Cellular component: cytosol; membrane; plasma membrane
Genetic constraint (gnomAD): Loss-of-function variants: 35 observed, 76.04 expected, observed/expected ratio (o/e) 0.46, 90% interval 0.35 to 0.61. The upper end of that interval is the gene's LOEUF score, 0.61, which puts it in group 2 of 6, group 1 being the genes least tolerant of losing a copy. Missense variants: 514 observed, 801.58 expected, observed/expected ratio (o/e) 0.64, 90% interval 0.6 to 0.69. Synonymous variants: 294 observed, 294.62 expected, observed/expected ratio (o/e) 1, 90% interval 0.91 to 1.1.
Homologues: Orthologues: chimpanzee ABCF2 (100% identical), guinea pig ABCF2 (99% identical), macaque ABCF2 (99% identical), mouse Abcf2 (99% identical), rat Abcf2 (99% identical), pig ABCF2 (99% identical), dog ABCF2 (98% identical), tropical clawed frog abcf2 (88% identical), zebrafish abcf2a (86% identical), zebrafish abcf2b (86% identical), Drosophila melanogaster CG9281 (68% identical), Caenorhabditis elegans abcf-2 (62% identical). Paralogues in human: ABCF1 (39% identical), ABCF3 (38% identical).
Diseases named in the same sentence as ABCF2 in open-access papers:
ABCF2 is named in the same sentence as 19 diseases in open-access papers, as found by Europe PMC text mining. Sharing a sentence is not in itself a finding about the gene and the disease. The quoted sentences say what the papers report.
ovarian carcinoma (6 papers, 2008 to 2024). A malignant neoplasm originating from the surface ovarian epithelium. "For instance, ABCF2 is a Nrf2 target gene contributing to cisplatin resistance in ovarian cancer cells." (PMID 35412955, 2022). "Although the ABCF2 gene is amplified in a chemoresistant ovarian cancer cell line (t24/cDDp10) with chromosome gain at 7q34–36, its role in tumour biology remains to be established." (PMID 19002184, 2008). "In ovarian cancer, ABCF2 protein expression was related with histologic types (significantly higher in clear-cell type compared with other histologic types)." (PMID 19002184, 2008). "Clinically, a copy number abnormality was reported in 20% of the patients with ovarian cancer including claudin 4 (CLDN4), RAS oncogene family (RAB25), and ATP binding cassette subfamily F member 2 (ABCF2)." (PMID 33076944, 2020). "Due to the presence of these data, it has been suggested that ABCF2 may be a novel NRF2 target gene, playing an important role in cisplatin resistance in ovarian cancer." (PMID 38434765, 2024). "The ovarian cancer cell line overexpresses NRF2, which also exhibited elevated levels of ABCF2." (PMID 38434765, 2024). "Furthermore, ABCF2 overexpression decreases apoptosis and increases cell viability following cisplatin treatment, indicating ABCF2 as a novel NRF2 target gene, playing a critical role in cisplatin resistance in ovarian cancer." (PMID 35453348, 2022). "In cervical cancer and clear cell types of ovarian cancer, ABCF2 expression was related with survival, however, in endometrial cancer and other histologic types of ovarian cancer, its expression was not related with survival." (PMID 19002184, 2008).
breast carcinoma (3 papers, 2008 to 2022). "ABCF2 may function in tumor suppression at the metastatic site of breast cancer (BC) and the endocrine pathway of BC and be implicated in BC’s chemotherapy resistance." (PMID 35412955, 2022). "In ovarian CCC, ABCF2 expression was associated with chemoresistance and OS, while in breast cancer, lack of ABCF2 expression was associated with increased disease-free survival." (PMID 19002184, 2008). "Recently, we reported that ABCF2 expression was related to prognosis in ovarian CCC and breast cancer." (PMID 19002184, 2008).
E. coli infection (2 papers, 2023 to 2025). "CASP14 and ABCF2 are involved in the pathogenic Escherichia coli infection (P = 0.0792)." (PMID 40029616, 2025).
cervical cancer (1 paper, 2008). A primary or metastatic malignant neoplasm involving the cervix. "In cervical cancer, ABCF2 expression was higher in stages III and IV than stages I and II tumours but expression was not related to histology or age of the patients." (PMID 19002184, 2008). "Among cervical cancer cases, 149 (55.8%) were cytoplasmic ABCF2 positive." (PMID 19002184, 2008). "In conclusion, ABCF2 expression may be a useful prognostic marker in cervical cancer but its expression is not related to prognosis and clinical factors in endometrial cancer." (PMID 19002184, 2008).
chorioamnionitis (1 paper, 2018). A morphologic finding indicating inflammation of the fetal sac membranes. "ABCB9, ABCC2 and ABCF2 were also up-regulated by chorioamnionitis though very little is known concerning the potential function of these transporters in the placenta." (PMID 29402780, 2018). "Up-regulation of ABCB9, ABCC2 and ABCF2 mRNA was detected in chorioamnionitis (p<0.05), whereas placental ABCB1 (P-gp; p=0.051) and ABCG2 (breast cancer resistance protein-BCRP) mRNA levels (p=0.055) approached near significant up-regulation." (PMID 29402780, 2018). "Similarly, there was a significant correlation between the severity of chorioamnionitis and the increased expression of ABCB1, ABCC2, ABCF2 and ABCG2." (PMID 29402780, 2018).
clear cell adenocarcinoma (1 paper, 2008). A malignant neoplasm composed of glandular epithelial clear cells. "We have produced an antibody to the ATP-binding cassette superfamily F (ABCF2) protein and demonstrated that ABCF2 protein expression is higher in clear cell adenocarcinoma (CCC) of the ovary than in other histologic types and may predict chemotherapy response and prognosis." (PMID 19002184, 2008).
clear cell ovarian adenocarcinomas (1 paper, 2025). "Elevated ABCF2 DNA copy number and mRNA levels are observed in clear cell ovarian adenocarcinomas compared to serous ovarian cystadenocarcinomas, correlating with chemotherapy response and prognosis in clear cell adenocarcinoma of the ovary." (PMID 40149433, 2025).
endometrial cancer (1 paper, 2008). Primary or metastatic malignant neoplasm involving the endometrium (mucous membrane that lines the endometrial cavity). "In this study, we evaluate the relationship between ATP-binding cassette superfamily F2 (ABCF2) expression and clinical factors including clinical stage, histologic type, grade and prognosis in uterine cervical and endometrial cancer." (PMID 19002184, 2008). "In this study, we examined the relationship between ABCF2 expression, clinical factors and prognosis in cervical and endometrial cancer." (PMID 19002184, 2008). "In this study, we evaluate the relationship between ABCF2 expression and clinical stage, histologic type, histologic grade and prognosis in uterine cervical and endometrial cancer." (PMID 19002184, 2008). "Among endometrial cancer cases, 72 (69.9%) were cytoplasmic ABCF2 positive." (PMID 19002184, 2008). "In contrast, ABCF2 expression was not related to OS and clinical factors such as age, stage, histologic type, histologic grade and oestrogen receptor status in endometrial cancer." (PMID 19002184, 2008).
hepatocellular carcinoma (1 paper, 2023). A malignant tumor that arises from hepatocytes. "Reference 1 Gao J, Dai C, Yu X, Yin X-B, Zhou F. Circ-TCF4.85 silencing inhibits cancer progression through microRNA-486-5p-targeted inhibition of ABCF2 in hepatocellular carcinoma." (PMID 37231579, 2023).
renal cell carcinoma (1 paper, 2022). "MiR-4731-5p can target circEHD2 and ABCF2, thus providing a novel and effective therapeutic against renal cell carcinoma." (PMID 35412955, 2022). "The current study hypothesized that circEHD2 induces renal cell carcinoma resistance to sunitinib via microRNA-4731-5p/ABCF2 axis." (PMID 35412955, 2022). "The use of miR-4731-5p to target circEHD2 and ABCF2 might provide a novel and effective therapeutic against renal cell carcinoma." (PMID 35412955, 2022). "The study hypothesized that circEHD2 induces renal cell carcinoma resistance to sunitinib via microRNA-4731-5p/ABCF2 axis." (PMID 35412955, 2022).
cancer (7 papers, 2008 to 2024). A tumor composed of atypical neoplastic, often pleomorphic cells that invade other tissues. "The expression levels of ABCA2, ABCC4, ABCD3, and ABCF2 in human skin were similar between normal and cancer individuals." (PMID 25505559, 2013). "ABCF2 is a member of the ABCF transporter family, a subgroup of the ATP binding cassette transporter superfamily, and is linked with drug resistance in several cancers." (PMID 35412955, 2022). "The role of ABCF2 protein may differ depending on the type of cancer." (PMID 19002184, 2008). "We further performed Q-RT-PCR to determine the mRNA expression levels of ABCA2, ABCC1, ABCC4, ABCD3, and ABCF2, which are the ABC transporters expressed in all of the skin samples in our semi-quantitative RT-PCR, in normal and cancer skin." (PMID 25505559, 2013). "Although ABCF2 is unable to act as a membrane transporter owing to the absence of transmembrane domains, ABCF2 can mediate cisplatin resistance in cancer cells." (PMID 31861937, 2019). "Some selected genes with high discriminative ability, belonging to three cancer-relevant pathways, such as ATP-binding cassette (ABC) family of genes (ABCA4, ABCA8) were identified as prospective gene markers of lung AC other one (ABCB1, ABCC3 and ABCF2) should be also under serious consideration." (PMID 22369099, 2011).
tumour (3 papers, 2008 to 2022). "Thus, the role of ABCF2 may differ according to tumour type." (PMID 19002184, 2008). "Moreover, it is known a direct action of NRF2 on proteins involved in chemoresistance such as AKR1C1-3, ABCF2, SLC40A1, as well as on the modulation of important growth factor receptors, such as c-MET, ErbB2 and EGFR regulating tumour growth." (PMID 35453348, 2022).
infection (2 papers, 2018 to 2024). The state of being infected such as from the introduction of a foreign agent such as serum, vaccine, antigenic substance or organism. "Another study showed that EspF binds to Abcf2 of the ABC transporter family, and during infection, Abcf2 is degraded in an EspF-dependent manner, resulting in increased cleavage of caspase-9 and caspase-3, promoting apoptosis." (PMID 39544522, 2024).
bacterial infection (1 paper, 2021). "To investigate how bacterial infection impacts placental efflux transport potential, we investigated the expression of the of Abca1, Abcb1a, Abcb1b, Abcb4, Abcc2, Abcc5, Abcf2, Abcg1 and Abcg2 mRNAs in the mouse placenta at GD15.5 or GD18.5 following LPS challenge (4 h)." (PMID 34394055, 2021).
ABCF2 also shares sentences with these, for which no sentence is quoted: interstitial cystitis (1 paper); neuropathy (1); resistant hypertension (1); uterine cancer (1); viral infection (1).